STAR (steroidogenic acute regulatory protein)
Diseases named in the same sentence as STAR in open-access papers (continued):
Sharing a sentence is not in itself a finding about the gene and the disease.
diabetes (5 papers, 2010 to 2025). "We also showed that diabetes caused an increase of steroidogenic enzyme StAR in the adrenal glands, in parallel to a rise in the plasma corticosterone levels, compared to the non-diabetic ones (respectively)." (PMID 36465619, 2022). "The human StAR gene (steroidogenic acute regulatory protein, synonym: cholesterol trafficker) has a known SNP marker (rs544850971) of hypertension in diabetes." (PMID 28105927, 2016). "Induction of diabetes decreased testicular StAR mRNA expression by 66% and MAE treatment enhanced mRNA expression to the same level of the control group." (PMID 24644381, 2014). "The biological implications of StAR upregulation are profound, as this protein directly influences the capacity for testosterone production and may potentially counteract diabetes-induced steroidogenic deficits." (PMID 40601674, 2025). "Diabetes did not alter StAR expression; however, StAR expression was reduced in the diabetic rats following ghrelin administration (P < 0.05)." (PMID 40601674, 2025).
hyperandrogenism (5 papers, 2016 to 2023). Excessive secretion of androgens from the adrenal glands or gonads. "BPA administration has been associated with modifications of ovarian steroidogenic enzymes including 17β hydroxylase, cholesterol side chain cleavage enzyme and steroidogenic acute regulatory protein, some of which are also implicated in PCOS hyperandrogenism." (PMID 36676087, 2023). "Because the StAR protein is involved in cholesterol transfer and steroidogenesis, a change in its gene expression can result in hyperandrogenism, which is one of the most common symptoms of PCOS." (PMID 35871495, 2022). "AGEs are associated with hyperandrogenism in PCOS possibly by altering the activity of various enzymes such as cholesterol side-chain cleavage enzyme cytochrome P450, steroidogenic acute regulatory protein, 17α-hydroxylase, and 3β-hydroxysteroid dehydrogenase." (PMID 27769286, 2016).
21-hydroxylase deficiency (4 papers, 2022 to 2025). "Although pathogenic variants have been identified in several genes, including CYP11B1, CYP17A1, HSD3B2, POR, STAR, and CYP11A1, approximately 95% of CAH cases are caused by 21-hydroxylase deficiency (21-OHD), primarily due to mutations in the CYP21A2 gene." (PMID 41440812, 2025). "Thus, inborn errors from cortisol biosynthesis such as StAR-defect, P450 side chain cleavage defect, 3β-hydroxysteroid dehydrogenase deficiency, 21-hydroxylase deficiency, 11-hydroxylase deficiency, 17-hydroxylase/17,20 lyase deficiency, and Smith Lemli Opitz syndrome could be excluded." (PMID 35627102, 2022). "After 21-hydroxylase deficiency, with 243 patients from 207 families, 3βHSD2 deficiency was the next most common form of CAH, accounting for 5% of cases, and was more frequent than 11-βhydroxylase deficiency (13 patients from 8 families) and StAR protein deficiency (6 patients from 4 families)." (PMID 35757411, 2022).
Follicular Cyst (4 papers, 2016 to 2023). Cyst due to the occlusion of the duct of a follicle or small gland. "The Kyoto Encyclopedia of Genes and Genomes (KEGG) analysis linked the ovarian steroidogenesis pathway, especially the STAR, 3β-HSD, CYP11A1 and CYP17A1 genes, to the formation of follicular cysts (p < 0.01)." (PMID 37958056, 2023). "Here, during the formation of porcine follicular cysts, excess cortisol might have affected the mRNA expressions of StAR, CYP11A1, and 3β-HSD, resulting in abnormally elevated levels of progesterone in FF." (PMID 35158681, 2022). "In this study, through transcriptomic analysis of TIMG cells, we found that StAR and CYP11A1, as well as CYP17A1 and 3β-HSD were significantly enriched in the signaling pathway of cortisol synthesis and secretion in follicular cysts." (PMID 38274662, 2023).
hepatocellular carcinoma (4 papers, 2014 to 2024). A malignant tumor that arises from hepatocytes. "Patients with NASH and NASH-driven hepatocellular carcinoma have also been reported to have increased hepatic StAR expression." (PMID 37490042, 2023).
Hyperglycemia (4 papers, 2013 to 2025). An increased concentration of glucose in the blood. "Likewise, in our study, we have seen a significant decrease in StAR gene expression resulting from moderate hyperglycemia and increased ROS activity within DM group." (PMID 38885232, 2024). "High glucose (HG) significantly suppressed both the StAR and LHR expression in dose- and time-dependent manners, indicating that hyperglycemia inhibits steroidogenic capacity and maturation." (PMID 40940788, 2025).
prostate carcinoma (4 papers, 2017 to 2025). A carcinoma that arises from epithelial cells of the prostate gland. "While this is not established in ACC tumors, de novo steroidogenesis has been shown to increase after treatment of androgen receptor–positive prostate cancer cells with IGF-2 via upregulated expression of steroid acute regulatory protein (StAR) as well as other steroidogenic enzymes." (PMID 40270996, 2025).
adrenocortical cancer (3 papers, 2012 to 2025). "Moreover, E199A alone as well as combination with K194R enhanced NR5A1-mediated STAR protein levels in mouse adrenocortical cancer Y1 cells." (PMID 24232453, 2013). "Interestingly, however, when used on NCI-H295R human adrenocortical carcinoma cells, efonidipine increased the expression of StAR mRNA and protein, possibly resulting in the increased production of DHEA-S." (PMID 23097668, 2012). "Both the expression of StAR at mRNA and protein levels and its activity were shown to be increased by nifedipine and efonidipine in MA-10 mouse Leydig cells and NCI-H295R human adrenocortical carcinoma cells, but decreased by amlodipine, azelnidipine, or R(-)-efonidipine." (PMID 23097668, 2012).
COVID-19 (3 papers, 2022 to 2025). A disease caused by infection with severe acute respiratory syndrome coronavirus 2. "Reduction in the expression of LHR, STAR, 3BHSD, and 17BHSD in the testis of COVID-19 patients was consistent with the observed low number of Leydig cells." (PMID 36797789, 2023). "Moreover, in the testis of patients who died from COVID-19, the levels of StAR, 3β-HSD, and 17β-HSD were significantly reduced and associated with low intratesticular testosterone levels, corroborating our findings." (PMID 40496014, 2025).
cyst (3 papers, 2010 to 2023). A sac-like closed membranous structure that may be empty or contain fluid or amorphous material. "Abundance of mRNA encoding PGRb, AR and STAR was significantly increased in GCs from cysts compared to control GCs, and mRNA levels for both LHCGR and FSHR were significantly lower in cyst CGs in comparison to controls (p < 0.05)." (PMID 37760251, 2023). "Based on the mouse knockout phenotypes, mutations involving the NOBOX, DMRT4, NR5A1 or StAR genes could be associated with cyst formation, however we did not detect mutations in the coding sequences of these genes in any of the cases described here." (PMID 20593028, 2010).
glioma (3 papers, 2020 to 2025). A benign or malignant brain and spinal cord tumor that arises from glial cells (astrocytes, oligodendrocytes, ependymal cells). "A pan-cancer analysis revealed that STAR is expressed not only in ovarian cancer but also in other tumors, such as head and neck squamous cell carcinoma (HNSC), testicular germ cell tumors (TGCT), low-grade glioma (LGG), and lung squamous cell carcinoma (LUSC)." (PMID 40098624, 2025). "In our study, we showed that StAR and CYP11A1 did not display any significant circadian variations in glioma cells, whereas TSPO levels followed a circadian rhythm in vitro and in vivo (mouse brain lysates)." (PMID 33086741, 2020).
hypogonadism (3 papers, 2015 to 2024). A disorder characterized by decreased function of the gonads. "We further established that the type of “hypogonadism” is primary in Sickle mice (based on elevated LH levels) and identified a possible basis for the testicular defect resulting in impaired steroidogenesis (involving reduced StAR protein expression and impaired Leydig cell function)." (PMID 26023917, 2015). "Intermittent hypoxia has been shown to induce upregulation of NADPH oxidase catalytic subunit gp91phox and regulatory subunits p22phox and p47phox in the testis; the effect of oxidative stress decreases mRNA and protein expressions of StAR and 3β-HSD and results in hypogonadism." (PMID 26023917, 2015).
ovarian carcinoma (3 papers, 2013 to 2025). A malignant neoplasm originating from the surface ovarian epithelium. "Despite these findings, the role of STAR in ovarian cancer, particularly in SOC, remains largely unexplored." (PMID 40098624, 2025). "Further analysis of the relationship between STAR expression and the clinical prognosis of SOC patients revealed that, in the overall ovarian cancer cohort, patients with high STAR expression had significantly longer overall survival (OS) compared to those with low STAR expression." (PMID 40098624, 2025). "In addition, real-time PCR studies on epithelial ovarian cancers suggest that StAR mediated progesterone biosynthesis may inhibit OSE tumor cell proliferation." (PMID 23291911, 2013). "Secondly, the top six genes, each with more than 100 publications (KIT, EGF, STAR, GAL, FGF2, VIP), have known established roles in ovarian cancer." (PMID 40699804, 2025). "We have previously shown that while human SF-1 and StAR are expressed in normal OSE cells, ovarian cancer cell lines SKOV-3, OVCar3 and BG1 do not show SF-1 or StAR expression." (PMID 23291911, 2013).
primary adrenal insufficiency (3 papers, 2017 to 2022). A hormonal disorder that occurs when the adrenal glands fail to release adequate amounts of glucocorticoids (cortisol), mineralocorticoids (aldosterone, 11-deoxycorticosterone), and androgens (dehydroepiandrosterone) to meet physiologic needs, despite release of ACTH from the pituitary. "Importantly, the findings from the urinary steroid profiling analysis were instrumental in excluding other causes of primary adrenal insufficiency (i.e. mutations in NR5A1, StAR, CYP11A1 or HSD3B2)." (PMID 34524979, 2021).
Sepsis (3 papers, 2021 to 2022). Sepsis is defined as life-threatening organ dysfunction caused by a dysregulated host response to infection. "For example, the expression of steroidogenic acute regulatory protein (StAR) activity early in sepsis can affect this part of steroidogenesis by reducing the transport of cholesterol from the outer to the inner mitochondrial membrane." (PMID 36345013, 2022). "Markers of adrenal uptake and synthesis of cholesterol (HDL-R and LDL-R, HMG-CoA reductase, StAR) were all elevated during all phases of sepsis-induced critical illness (p < 0.01 for all sepsis groups)." (PMID 33593393, 2021). "Moreover, VD can significantly increase the mRNA expression of STAR, CYP17A1, and CYP21 proteases in adrenal cortex cells, and intragastric administration of VD to sepsis model rats can increase the serum cortisol level in vivo." (PMID 36338128, 2022).
Adrenocortical Adenoma (2 papers, 2016 to 2023). "In addition, FADS2 expression positively correlated with STAR expression in aldosterone- and cortisol-producing adrenocortical adenomas." (PMID 37478183, 2023).
breast tumor (2 papers, 2023 to 2024). "We recently reported that hormone-sensitive human breast tumors, as well as BC cell lines, possess higher expression of the StAR protein, compared with their normal counterparts or TNBCs." (PMID 39201419, 2024). "StAR, ERα, ERβ, and PR mRNA levels were undetectable in breast tumors obtained from TNBC mice, confirming that these tumors are hormone-independent." (PMID 36614200, 2023). "As determined by semi-quantitative RT-PCR, expression of StAR mRNA was evidently high in breast tumors induced by Neu, HRAS, and PyMT oncogenes, when compared with either TNBC or normal mouse mammary tissue." (PMID 36614200, 2023). "Second, primary human breast tumor tissue cDNA array showed higher expression of StAR mRNA in ER+/PR+ subtypes in comparison to its modest levels in TNBCs and normal mammary epithelial tissue." (PMID 36614200, 2023). "An intriguing aspect of the present study is the inhibition of StAR expression and subsequent reduction in E2, by various HDACIs, in primary cultures of enriched breast tumor epithelial cells isolated from MMTV-PyMT mice." (PMID 36614200, 2023). "As determined by RT-qPCR, expression of StAR mRNA was 4.6 ± 1.7-fold higher in breast tumors of MMTV-PyMT mice, when compared with normal mouse mammary tissues." (PMID 36614200, 2023). "Third, three different Tg mouse models of spontaneous breast tumors documented aberrantly high expression of StAR, along with E2 accumulation, in hormone-sensitive breast tumors, over the levels seen in either TNBCs or normal mammary tissue." (PMID 36614200, 2023). "A novel aspect of the present findings is the abundant expression of StAR, along with E2 accumulation, in three different Tg mouse models of spontaneous breast tumors driven by MMTV-Neu (HER+), MMTV-HRAS (ER+), and MMTV-PyMT (ER+/PR+)." (PMID 36614200, 2023). "Breast tumors in this Tg mouse line are hormone-sensitive and display abundant expression of StAR, along with elevated E2 synthesis." (PMID 36614200, 2023). "Whereas StAR was found to be distinctly expressed in human and/or mouse hormone-sensitive breast tumor cells and tissues, an involvement of STARD3, a late endosomal membrane protein with ~37% C-terminal homology to StAR, cannot be excluded." (PMID 36614200, 2023). "MMTV-HRAS-driven breast tumors showed comparatively lower expression of StAR mRNA." (PMID 36614200, 2023). "In pursuance of these data, we are currently generating antibodies to acetylated and deacetylated forms of StAR with K111Q, K253Q, K111R, and K253R, which could serve as molecular tools for BC screening/diagnosis and the regression of breast tumors, respectively." (PMID 39201419, 2024). "Noteworthy, inhibition of StAR expression, corresponding with a reduction in E2 biosynthesis, by a variety of HDACIs, in both hormone-sensitive human MCF7 cells and mouse enriched breast tumor epithelial cells, demonstrated that StAR could be targeted for combating ER+ BC." (PMID 36614200, 2023). "Treatment with a variety of histone deacetylase inhibitors (HDACIs) in primary cultures of enriched breast tumor epithelial cells, from MMTV-PyMT mice, resulted in suppression of StAR and E2 levels." (PMID 36614200, 2023). "Since breast tumors in MMTV-PyMT Tg mice were identified as ER+/PR+, we determined expression of both StAR and aromatase levels, and their correlation to E2 biosynthesis." (PMID 36614200, 2023). "Additionally, three different transgenic (Tg) mouse models of spontaneous breast tumors, i.e., MMTV-Neu, MMTV-HRAS, and MMTV-PyMT, demonstrated markedly higher expression of StAR mRNA/protein in breast tumors than in normal mammary tissue." (PMID 36614200, 2023). "Whereas expression of the StAR protein was little to none in normal mammary tissue, its level was markedly high (p < 0.001) in breast tumors of MMTV-PyMT mice." (PMID 36614200, 2023).
breast tumor (continued). "We reported that StAR expression, along with E2 synthesis, is aberrantly high not only in human hormone-dependent BC cells, but also in transgenic mouse models of spontaneous breast tumors, in comparison with little to no expression of StAR in their non-cancerous counterparts or TNBC." (PMID 39201419, 2024). "Utilizing hormone-dependent and hormone-independent human breast cell lines, while a number of StAR acetylomes were identified, either endogenously or in response to various HDACIs, using LC-MS/MS, no acetylated StAR lysine residues were verified in primary breast tumors." (PMID 39201419, 2024).
esophageal cancer (2 papers, 2019 to 2025). A primary or metastatic malignant neoplasm involving the esophagus. "Previous research showed that chemotherapy reduced STAR expression in granulosa cells in normal ovaries, and in esophageal cancer, elevated STAR expression was linked to chemotherapy resistance." (PMID 40098624, 2025). "Of note, the late endosomal membrane protein STARD3 (also known as metastatic lymph node 64), with ~37% C-terminal homology to StAR, was initially cloned as a gene amplified in the breast, gastric, and esophageal cancers." (PMID 31060224, 2019).
hypergonadotrophic hypogonadism (2 papers, 2022). "A similar phenomenon akin to that seen in 46,XX individuals with STAR variants may occur, where enzyme deficiency is either compensated for, or girls progress through puberty appropriately but hypergonadotrophic hypogonadism ensues thereafter." (PMID 35904228, 2022).
Hypoglycemia (2 papers, 2021). A decreased concentration of glucose in the blood. "Partial loss of CYP11A1 or STAR can present in childhood with ketotic hypoglycemia." (PMID 34258490, 2021). "To exclude the possibility that StAR up-regulation and mimecan down-regulation are induced by insulin itself, rather than by insulin-induced hypoglycemia stress, we examined the StAR and mimecan mRNA levels after insulin stimulation in Y1 cells." (PMID 33971622, 2021).
Insulin resistance (2 papers, 2020 to 2024). Increased resistance towards insulin, that is, diminished effectiveness of insulin in reducing blood glucose levels. "Steroidogenic acute regulatory protein (StAR), a mitochondrial cholesterol delivery protein, plays a protective role in systemic inflammation and insulin resistance in obese mice." (PMID 38885232, 2024). "The expression of StAR is attenuated in a HF-fed mice and over expression of StAR improves insulin resistance induced by a HF diet." (PMID 31941510, 2020).
Klinefelter syndrome (2 papers, 2021 to 2022). A sex chromosome disorder caused by the presence of an extra X chromosome in the male karyotype. "Similarly, overexpression of HSD17B1 and StAR protein was observed in testes of men with Klinefelter syndrome, suggesting overactivation of the hormones’ biosynthetic pathway in Leydig cells." (PMID 35336747, 2022).
melanoma (2 papers, 2019 to 2024). A malignant, usually aggressive tumor composed of atypical, neoplastic melanocytes. "In melanoma and uterine endometrial carcinomas, five (368 tumors; 1.36%) and four (248 tumors; 1.61%) mutations were observed in the StAR gene, respectively." (PMID 31060224, 2019).
ovarian dysfunction (2 papers, 2021 to 2024). The inability of the ovaries to function. "In contrast, when incubated with the StAR promoter, a faint band was detected in the mutant FOXL2 [c.223C > T; p.(Leu75Phe), c.293G > A; p.(Trp98Ter), c.307C > T; p.(Arg103Cys), c.383G > A; p.(Trp128Ter), and c.415G > T; p.(Gln139Ter)] group, which may be a predictor of ovarian dysfunction." (PMID 33796131, 2021).
Primary amenorrhea (2 papers, 2011 to 2021). "In the successful pregnancies in CAH women caused by 17-hydroxylase deficiency and steroidogenic acute regulatory protein mutations, the patients presented with primary amenorrhea and absent or incomplete sexual maturation." (PMID 33526062, 2021). "Defects in the steroidogenic acute regulatory enzyme(StAR), CYP17, and aromatase enzymescause primary amenorrhea and POF." (PMID 24963360, 2011).
viral infection (2 papers, 2019 to 2025). "It will be important to elucidate the role of other known lipid transport proteins including steroidogenic acute regulatory protein (StAR) and Oxysterol-binding protein-related protein 1A and B (OSBPL1A) in the formation of replication organelle during NPEV viral infections." (PMID 31215493, 2019).
adenomyosis (1 paper, 2020). The growth of endometrial tissue inside the muscular wall of the uterine corpus. "In addition, genes involved in estrogen biosynthesis, such as steroidogenic acute regulatory protein (StAR) and P450 aromatase, are upregulated in adenomyosis." (PMID 32050720, 2020).